ACAN (aggrecan)
Diseases named in the same sentence as ACAN in open-access papers (continued):
Sharing a sentence is not in itself a finding about the gene and the disease.
epithelial ovarian cancer (2 papers, 2013 to 2020). "Syndecan-3- and aggrecan-peptides were recently described as novel biomarkers for the detection of epithelial ovarian cancer." (PMID 32351878, 2020). "Aggrecan expression is enhanced in many cancers and has been reported to influence ovarian cancer growth and metastasis." (PMID 24312594, 2013). "The cleavage of proteoglycans like aggrecan and versican by a disintegrin and metalloproteinase with thrombospondin motifs (ADAMTS) in epithelial ovarian cancer has been demonstrated and is considered of prognostic value." (PMID 32351878, 2020).
glioma (2 papers, 2024 to 2025). A benign or malignant brain and spinal cord tumor that arises from glial cells (astrocytes, oligodendrocytes, ependymal cells). "All three DEGs encoding proteoglycans (HAPLN2, ACAN and HAPLN1) showed higher transcript enrichment in the grade 2 gliomas in comparison to the matched normal samples." (PMID 41366031, 2025). "In comparison to normal tissue, spatial enrichment for SMOC1, ACAN, and SEMA6A transcripts was evident in cells of grade 2 glioma samples." (PMID 41366031, 2025).
growth disorder (2 papers, 2023 to 2025). "Our data documents a more than tenfold decline in ACAN levels starting at age 12–13 years for female adolescents and 13–14 years for male adolescents, offering the potential for early growth disorder diagnostics." (PMID 39972214, 2025). "All these variants were identified in genes already associated with growth disorders: PROKR2 (N = 2), PTPN11 (N = 6), ANKRD11 (N = 1), NPR2 (N = 1), NF1 (N = 1), ACAN (N = 1), GH1 (N = 1), FBN1 (N = 1), COMP (N = 1), IGF1R (N = 1), ARID1A (N = 1), and CASR (N = 1)." (PMID 37605180, 2023).
hearing loss (2 papers, 2016 to 2024). "The genes ARHGEF28, SYNJ2, and ACAN have been previously implicated in common variant studies of hearing loss (GWAS)." (PMID 38943082, 2024).
Hyperglycemia (2 papers, 2021 to 2024). An increased concentration of glucose in the blood. "Moreover, the addition of a high glucose level to PA at 0.1 mM further supported the trend of PA to decrease the mRNA level of aggrecan previously found under normoglycemic conditions (p = 0.015 between PA-treated cells under normo- and hyperglycemia)." (PMID 38339087, 2024). "Additionally, gene and protein levels of chondrogenic markers including SOX9, type 2 collagen (Col II) and aggrecan (AGN) were significantly decreased, indicating the chondro-inhibitory nature of hyperglycemia." (PMID 34685425, 2021).
infertile (2 papers, 2023). "In tri-lineage differentiation, menstrual blood-derived cells from both volunteers and infertile patients expressed FABP-4 for adipogenesis, osteocalcin for osteogenesis, and aggrecan for chondrogenesis." (PMID 37840125, 2023).
keloid (2 papers, 2010 to 2020). An irregularly shaped, elevated mark on the skin caused by deposits of excessive amounts of collagen during wound healing. "A statistically significant (P < .05) differential expression and a fold change of more than 2 were determined between keloid margin and internal control biopsy samples for 10 genes, including ACAN, ASPN, C5orf13, HIF1A, IGFBP7, INHBA, LGALS1, PTN, SERPINH1, and TNFAIP6." (PMID 20418938, 2010). "ACAN and TNFAIP6 were found to interact with hyaluronic acid in keloid fibroblasts when upregulated but are not well studied in keloid or skin." (PMID 32085797, 2020).
laryngeal carcinoma (2 papers, 2017 to 2018). Carcinoma that arises from the laryngeal epithelium. "In this regard, degradation of two well-known ADAMTS-5 substrates such as brevican and aggrecan facilitate tumor progression in glioblastoma and laryngeal carcinoma, respectively." (PMID 28099917, 2017). "Thus, the hyalectan aggrecan is postulated as tumor suppressor as decreased aggrecan expression correlates with metastasis and poor prognosis in laryngeal cancer." (PMID 29559954, 2018).
lumbar disc herniation (2 papers, 2017 to 2025). "This study evaluated the association of single nucleotide variants (SNVs) of the candidate genes of the aggrecan metabolic pathway with the severity of lumbar disc herniation in patients with chronic mechanical low back pain." (PMID 28742099, 2017). "Our findings on the associations of SNVs of ACAN with the severity of lumbar disc herniation were further strengthened by the results of the haplotype analysis." (PMID 28742099, 2017). "Single nucleotide variants of ACAN and their haplotypes are associated with the severity of lumbar disc herniation." (PMID 28742099, 2017). "In our results, minor allele of the rs2272023 (C), rs35430524 (A), rs2882676 (A), rs2351491 (T), rs938609 (A), rs3825994 (G), rs1042630 (A), rs698621 (G) and rs3817428 (G) variants of ACAN were associated with the severity of lumbar disc herniation." (PMID 28742099, 2017). "The rs2272023, rs35430524, rs2882676, rs2351491, rs938609, rs3825994, rs1042630, rs698621 and rs3817428 variants and their haplotypes of ACAN were associated with the severity of lumbar disc herniation." (PMID 28742099, 2017). "The study assessed associations of SNVs of candidate genes of the aggrecan metabolic pathway with the severity of lumbar disc herniation in patients with chronic mechanical low back pain." (PMID 28742099, 2017). "In addition, haplotypes of rs938609 and rs2882676 loci, and haplotypes of rs3825994 and rs1042630 loci of ACAN were associated with the severity of lumbar disc herniation." (PMID 28742099, 2017). "SNVs of ACAN and their haplotypes are associated with the severity of lumbar disc herniation." (PMID 28742099, 2017). "Candidate genes of the aggrecan metabolic pathway may associate with the severity of lumbar disc herniation." (PMID 28742099, 2017).
lung adenocarcinoma (2 papers, 2022 to 2025). A carcinoma that arises from the lung and is characterized by the presence of malignant glandular epithelial cells. "The results showed that ACAN, CDKN3, GRIN2A, IL17A, KCNQ2, TIMP1, and UCHL1 were significantly up-regulated in lung adenocarcinoma cells." (PMID 36147496, 2022).
lung carcinoma (2 papers, 2024 to 2025). "Increased fibronectin, laminin, nidogen, and aggrecan have been previously associated with an aggressive phenotype and progression in lung cancer." (PMID 39058055, 2024).
Lyme disease (2 papers, 2013 to 2015). Lyme disease (named after the towns in the USA where the disease was first identified) is a bacterial infection caused by Borrelia burgdorferi. "A recent study describes for the first time an enzyme produced by the spirochetal agent of Lyme disease, Borrelia burgdorferi, that cleaves aggrecan, a proteoglycan found in joints and connective tissue." (PMID 23967405, 2013). "Borrelia burgdorferi synthesizes an HtrA protease (BbHtrA) which is a surface-exposed, conserved protein within Lyme disease spirochetes with activity toward CheX and BmpD of Borrelia spp, as well as aggrecan, fibronectin and proteoglycans found in skin, joints and neural tissues of vertebrates." (PMID 26076465, 2015).
mental disorder (2 papers, 2018 to 2019). A disease that has its basis in the disruption of mental process. "In the present study recapitulating a neurodevelopmental approach to the pathogenesis of psychiatric diseases, we observed that the numbers PV+ neurons associated with WFA+ and ACAN+ PNNs were reduced in the mPFC of HT-PS." (PMID 30233323, 2018).
Noonan syndrome (2 papers, 2020 to 2023). Noonan Syndrome (NS) is characterized by short stature, typical facial dysmorphism and congenital heart defects. "In particular, skeletal dysplasias (ACAN, MMP13 mutations) and Noonan syndrome (PTPN11) were detected." (PMID 32939436, 2020).
oligodendroglioma (2 papers, 2017 to 2018). A well-differentiated (WHO grade II), diffusely infiltrating neuroglial tumor, typically located in the cerebral hemispheres. "We found, for example, which cultured oligodendroglioma cells discard through EVs the histone variant H1.0, which might otherwise contribute to cell differentiation; on the other hand, the same EVs contain matrix metalloproteases able to digest aggrecan." (PMID 29261132, 2017). "For example, EVs shed by FLSs contain ADAMTS-5, which degrade aggrecan and facilitate oligodendroglioma and RA-FLSs to invade through aggrecan-rich ECM." (PMID 30322133, 2018). "Similarly, EVs released from oligodendroglioma cells in culture contain Adamts1, Adamts4 and Adamts5 active aggrecanases and, indeed, degrade aggrecan in a dose-dependent manner." (PMID 29261132, 2017).
Osteochondroma (2 papers, 2017 to 2024). A common, benign cartiliginous neoplasm arising from the metaphysis of bone. "In good correlation, osteochondromas developed in the cranial base of mutant Ext1f/f;Col2-CreER or Ext1f/f;Aggrecan-CreER mouse models of HME along the synchondrosis growth plates." (PMID 28445472, 2017).
osteogenesis imperfecta (2 papers, 2012 to 2025). Osteogenesis imperfecta (OI) comprises a heterogeneous group of genetic disorders characterized by increased bone fragility, low bone mass, and susceptibility to bone fractures with variable severity. "ECM has an essential role in skeletal development which is proven by numerous amounts of skeletal disorders arising through mutations in the genes encoding the structural proteins like aggrecan, perlecan or several types of collagens causing collagenopathies and osteogenesis imperfecta (OI)." (PMID 22815736, 2012).
osteosarcoma (2 papers, 2009 to 2022). A usually aggressive malignant bone-forming mesenchymal neoplasm, predominantly affecting adolescents and young adults. "In rat osteosarcoma cells and primary bovine chondrocytes, treatment with retinoic acid produces cleavage of aggrecan (ACAN) at the E373-A374 peptide bond that is also cleaved in OA." (PMID 19173746, 2009).
ovarian cancer (2 papers, 2013 to 2018). A primary or metastatic malignant neoplasm involving the ovary. "In another study, a higher ADAMTS-1, ADAMTS-5, aggrecan, versican and TIMP-3 expression in malignant ovarian tumors compared to benign tumors was associated with a shorter overall survival in ovarian cancer patients." (PMID 29393911, 2018).
scoliosis (2 papers, 2019 to 2020). A congenital or acquired spinal deformity characterized by lateral curvature of the spine. "Some researchers found that the imbalanced expression of sox9, collagen II, collagen X, and aggrecan on both sides of the spine may be the cause of scoliosis." (PMID 30886859, 2019). "On the contrary, in cultured NP cells from scoliosis patients leptin decreased the expression of aggrecan and induced the expression of catabolic aggrecanases via p38-MAPK pathway." (PMID 33396484, 2020). "In a study on cultured NP from four scoliosis patients (not LDD) leptin decreased the expression of aggrecan and induced the expression of aggrecanases via p38-MAPK pathway." (PMID 33396484, 2020).
Seizure (2 papers, 2018 to 2021). A seizure is an intermittent abnormality of nervous system physiology characterized by a transient occurrence of signs and/or symptoms due to abnormal excessive or synchronous neuronal activity in the brain. "Seizures also may lead to the degradation of aggrecan, a CS- and KS-rich proteoglycan, by matrix metalloproteinases (MMPs)." (PMID 34573906, 2021). "Indeed a number of seizure models show downregulation of the PNN components aggrecan, hyaluronan and proteoglycan link protein 1 (HAPLN1) and hyaluronan synthease-343." (PMID 30413686, 2018).
septic arthritis (2 papers, 2016 to 2019). "We report a case of a child with severe inflammatory elbow involvement mimicking septic arthritis who carried the new ACAN missense variant c.6970 T > C, p.Trp2324Arg." (PMID 31747937, 2019). "Our data indicate that collagen type 2 cleavage products (C2C), which possess pharmacodynamic and physiological relevance for cartilage degradation, are a more reliable parameter characterizing cartilage degradation in septic arthritis compared to aggrecan." (PMID 27688601, 2016).
stomach carcinoma (2 papers, 2018 to 2021). "That mutation of ACAN occurs in stomach carcinoma has been shown by comprehensive whole‐genome and transcriptome sequencing analysis." (PMID 29435418, 2018).
Stroke (2 papers, 2014 to 2018). Sudden impairment of blood flow to a part of the brain due to occlusion or rupture of an artery to the brain. "Here, we demonstrate that aggrecan, a key component of PNNs, undergoes increased digestion following stroke and EE conditions even in cortical regions remote from the lesion." (PMID 28290150, 2018). "Because aggrecan can be cleaved at multiple sites, several fragments were identified on the western blots from shams and stroke animals." (PMID 28290150, 2018).
thyroid cancer (2 papers, 2019 to 2024). "For example, the combined signal of MMP11 and MMP19, which both cleave aggrecan and gelatin, resulted in a larger area under the curve (AUC) value than individually in thyroid cancer." (PMID 39239548, 2024). "The combined signal of MMP11 and MMP19, both of which cleave aggrecan and gelatin, resulted in a higher AUC value than individually in thyroid cancer." (PMID 31200666, 2019).
Umbilical hernia (2 papers, 2020 to 2021). Protrusion of abdominal contents through a defect in the abdominal wall musculature around the umbilicus. "The ACAN gene, which had already been associated to the appearance of scrotal hernia, showed similar behavior in the data obtained from the umbilical hernia group." (PMID 33513662, 2021). "The results pointed out ACAN, MMPs, COLs, EPYC, VIT, CCBE1 and LGALS3 as strong candidates to trigger umbilical hernias in pigs since they act in the extracellular matrix remodeling and in the production, integrity and resistance of the collagen." (PMID 32379844, 2020). "From this set of genes, we highlight KRT14 (Keratin 14), CCBE1, ACAN, Desmoglein 2 (DSG2) and EPYC, which were more enriched in the anatomic development process in the gene network and were upregulated in animals affected by umbilical hernia." (PMID 32379844, 2020).
Acidosis (1 paper, 2021). Abnormal acid accumulation or depletion of base. "Acidosis increased the expression of MMP3 and MMP9, enzymes which break down ECM components and accordingly, there were decreased levels of both collagen II and aggrecan recorded under acidic conditions." (PMID 33824228, 2021).
acute lymphoblastic leukemia (1 paper, 2023). Leukemia with an acute onset, characterized by the presence of lymphoblasts in the bone marrow and the peripheral blood. "Several comparative proteomic studies have reported ACAN as a new serum tumor marker for hepatocellular or childhood acute lymphoblastic leukemia through regulation of the Hippo/YAP signalling pathway." (PMID 36918772, 2023).
aortic valve disease (1 paper, 2022). "In addition, we analyzed the protein localization of Sox9 and Aggrecan (key proteins implicated in the pathogenesis of aortic valve disease), as well as Wnt7a and Opg (which showed altered expression in RNASeq) using immunohistochemistry." (PMID 36005436, 2022).
Cerebral ischemia (1 paper, 2017). Restriction of arterial blood supply to the brain associated with insufficient oxygenation to support the metabolic requirements of the tissue. "Nagel and colleagues observed remodeling of aggrecan in individual neurons of a focal cerebral ischemia model, suggesting it plays a role in neuronal reorganization." (PMID 28262779, 2017).
cervical spondylosis (1 paper, 2014). "The results show that the expression levels of type II collagen and aggrecan in the cervical spondylosis group end-plates were significantly lower than those in the control group." (PMID 24520242, 2014). "The mRNA expression levels of the aggrecan gene (0.715±0.194) and the type II collagen gene (0.628±0.254) in the cervical spondylosis group were much lower than those in the control group (0.913±0.254 and 0.845±0.186, respectively)." (PMID 24520242, 2014). "The mRNA expression levels (relative to those of β-actin) of aggrecan (0.715±0.194) and type II collagen (0.628±0.254) in the cervical spondylosis group were markedly decreased compared with those in the control group (0.913±0.254 and 0.845±0.186, respectively; both P<0.05)." (PMID 24520242, 2014).
chondroblastic osteosarcoma (1 paper, 2011). An osteosarcoma characterized by the presence of atypical cartilage of variable cellularity. "The genes that make up the chondroblastic-specific part of this expression profile are mostly chondroid matrix-associated genes, such as ACAN, COL2A1, and MATN4, and are all upregulated in chondroblastic osteosarcoma." (PMID 21933437, 2011).
chronic kidney disease (1 paper, 2020). Impairment of the renal function secondary to chronic kidney damage persisting for three or more months. "Supporting this hypothesis, ACAN upregulation has been associated with vascular calcification and chronic kidney disease." (PMID 33425910, 2020).
chronic lymphocytic leukemia (1 paper, 2024). "These auto-Abs were against ACAN, a known biomarker in RA and ZMYM3 and RNF111, implicated in chronic lymphocytic leukemia and cancers, respectively." (PMID 38470480, 2024).
co-infection (1 paper, 2012). "We found that total GAG content in the satellite cells was significantly induced by Sox9 as well as Nkx3.2/Sox9 co-infection, which is consistent with the qRT-PCR analysis for aggrecan." (PMID 22768305, 2012). "This is further confirmed by our RT-PCR analysis that showed diminished expression of collagen II mRNA as well as aggrecan mRNA upon Nkx3.2ΔC-VP16 and Sox9 co-infection." (PMID 22768305, 2012).
collagenopathy (1 paper, 2022). "We compared the height Z score of collagenopathy patients with other different-causing gene mutations and found that the ACAN mutation resulted in milder short stature than the collagen gene mutation (p = .021), while the COMP mutation was the most severe (p = .009)." (PMID 35250876, 2022).
colon cancer (1 paper, 2018). "We identified versican (VCAN), a member of the aggrecan/versican proteoglycan family, as a key regulator in human colon cancer development and progression involved in cell adhesion, proliferation, migration and angiogenesis and plays a central role in tissue morphogenesis and maintenance." (PMID 30237752, 2018).
COVID-19 (1 paper, 2023). A disease caused by infection with severe acute respiratory syndrome coronavirus 2. "Moreover, high plasma levels of aggrecan (ACAN), the main component of cartilaginous ECM, may indicate the degradation of cartilaginous tissues after COVID-19 pro-inflammatory conditions." (PMID 37047248, 2023).
fetal hydrops (1 paper, 2025). "Increased NT or fetal hydrops was observed in 13/36 (36.1%) cases, including two cases of skeletal dysplasia (due to COL2A1 and ACAN variants) and two cases of spondylocostal dysostosis." (PMID 39674903, 2025).
Fuchs endothelial corneal dystrophy (1 paper, 2022). Fuchs endothelial corneal dystrophy (FECD) is the most frequent form of posterior corneal dystrophy (see this term) and is characterized by excrescences on a thickened Descemet membrane (corneal guttae), generalized corneal edema, with gradually decreased visual acuity. "In summary, the present study investigated the immunohistochemical expression pattern of tenascin-C, matrilin-2, and aggrecan in advanced forms of corneal endothelial pathology such as pseudophakic bullous keratopathy and Fuchs’ endothelial corneal dystrophy." (PMID 36294311, 2022).
glaucoma (1 paper, 2021). Increased pressure in the eyeball due to obstruction of the outflow of aqueous humor. "Remarkably, we found comparable protein and mRNA levels of these proteoglycans, which indicates a damage-independent expression of aggrecan and brevican in our glaucoma model." (PMID 33668263, 2021).